RNU6-879P (RNA, U6 small nuclear 879, pseudogene)
Gene: Small nuclear RNA gene on chromosome 12 (57,415,296 to 57,415,403, forward strand). Ensembl gene ENSG00000201198.
Homologues: Orthologues: chimpanzee U6 (100% identical), macaque U6 (97% identical), mouse Gm22055 (81% identical), guinea pig U6 (71% identical), dog U6 (68% identical), dog U6 (65% identical). Paralogues in human: RNU6-797P (90% identical), RNU6-1209P (86% identical), RNU6-1243P (86% identical), RNU6-727P (86% identical), RNU6-1091P (85% identical), RNU6-1094P (85% identical), RNU6-183P (85% identical), RNU6-511P (85% identical), RNU6-944P (85% identical), RNU6-992P (85% identical), RNU6-1175P (84% identical), RNU6-11P (84% identical), and 1287 more.